TGFBI (transforming growth factor beta induced)
Diseases named in the same sentence as TGFBI in open-access papers (continued):
Sharing a sentence is not in itself a finding about the gene and the disease.
cancer (continued). "We validated junctions from the cancer-associated genes UBE2C (chr20:44443109–44444493), and TGFBI (chr5:135390550–135390958) which were confirmed by the Integrative Genomics Viewer (IGV) using raw RNA-Seq data." (PMID 32437477, 2020). "Overexpression of UBE2C has been detected in many types of human cancers, and TGFBI is a candidate regulator of EMT." (PMID 32437477, 2020). "This epigenetic silencing of the TGFBI gene observed was in line with previous studies of other cancers." (PMID 31277676, 2019). "Several previous reports have indicated that TGFBI plays the role of a tumor suppressor gene in various cancers such as lung, breast, and ovarian." (PMID 31277676, 2019). "Comparison of TGFBI and Dkk-3 staining in cancer found high levels of TGFBI in some tumors that expressed low levels of Dkk-3, suggesting an inverse correlation." (PMID 29858602, 2018). "As a secreted protein that resides within the ECM, TGFBI affects cell migration and proliferation in models of cancer." (PMID 28750100, 2017). "The mechanism by which TGFBI induces EMT is unclear; however, TGFBI is positively or negatively associated with cancer cell proliferation and invasion depending on the cancer type." (PMID 28106769, 2017). "Among the proteins that were found to be upregulated in the cancer cell line secretome, transforming growth factor-beta-induced protein ig-h3 (beta ig-h3) and peroxiredoxin-2 (PRDX2) were the focal points of our study." (PMID 28261610, 2017). "In conclusion, SPARC regulates the fibrillar ECM deposition of TGFBI through a novel interaction, subsequently influencing cancer cell behavior." (PMID 27622658, 2016). "TGFBI is an extracellular matrix (ECM) protein induced by transforming growth factor-β (TGF-β) in human cancer cells." (PMID 26422603, 2015). "TGFBI is an extracellular protein that promotes epithelial-mesenchymal transition and cancer metastasis." (PMID 25889562, 2015). "TGFBI is a secreted extracellular matrix protein that is overexpressed by several cancer types, and is suggested to promote metastatic progression." (PMID 24708694, 2014). "The tumorigenicity of these cancer cell lines as determined by subcutaneous inoculation in nude mice was similarly suppressed by TGFBI expression." (PMID 22695319, 2012). "Our previous findings revealed that expression of TGFBI gene is down-regulated in a variety of cancer cell lines and clinical tissue samples." (PMID 22695319, 2012). "This stage-specific dual functional role of TGFBI in cancer represents an emerging paradigm whereas the mechanism behind is not well understood." (PMID 22695319, 2012). "Promoter hypermethylation is considered an important mechanism involved in the silencing of the TGFBI gene in human cancer cells." (PMID 22949874, 2012). "TGFBI expression was significantly (p = 0.003) higher in patients who responded to chemotherapy (average TGFBI H score = 170) compared to patients whose cancer progressed (average score = 110) or who had stable disease (average score = 120)." (PMID 20509890, 2010). "To address the importance of TGFBI expression in cancer progression, we determined its expression in NSCLC clinical samples using immunohistochemistry." (PMID 20509890, 2010). "But there is also mounting evidence that periostin and TGFBI can have complementary or opposite roles in cancer and development." (PMID 20109226, 2010). "At least 50 genes in our list are already known to be regulated by DNA methylation, such as those encoding cancer antigens (a set of MAGE and GAGE), H19, S100A4, IGFBP4, UCHL1, COL1A2, CLU, FN1, and TGFBI." (PMID 19234609, 2009). "Notably, TGFBI exhibits context-dependent oncogenic functions that vary among different cancer types." (PMID 40430059, 2025). "Subsequently, researchers tried to employ TGFBI as a biomarker for cancer prognosis." (PMID 38395907, 2024). "Furthermore, the mRNA expression and secretion of TGFBI were increased in the Cat D deletion cancer cells." (PMID 38297161, 2024).
cancer (continued). "Based on these results, single cell analysis revealed a remarkably higher TGFBI expression in TAMs or even cycling TAMs, so we presume that TGFBI can not only directly affect cancer cells, but also promote disease progression through TAMs, which proves its value as therapeutic targets." (PMID 39068456, 2024). "Given the suppressed metastasis and minor effects of TGFBI in the Cat D KO cancer-bearing mice, we hypothesized that Cat D-mediated TGFBI upregulation might have an additional and closely related role in the TME." (PMID 38297161, 2024). "Consequently, we selected five genes—INHBA, MMP7, PSAT1, SLC7A5, and TGFBI—to evaluate their mRNA expression levels in normal colon tissues compared to their corresponding cancer tissues." (PMID 39628390, 2024). "Recently, growing evidence supported the abnormal TGFBI expression in cancer." (PMID 38395907, 2024). "In contrast, TGFBI blockade recovered the CD204+ TAM polarization induced by Cat D KO cancer cells." (PMID 38297161, 2024). "Furthermore, CD204+ TAMs primed using parent cancer cells were reduced following TGFBI protein treatment." (PMID 38297161, 2024). "TGFBI's impact extends beyond mere correlations, encompassing critical aspects such as chemotaxis, migratory potential, proliferation, apoptosis, metastatic niche promotion, cancer cell adhesion, and aberrant angiogenesis in other types of cancer." (PMID 38514830, 2024). "The necessity of TGFBI in the development of cancer has been approved by numerous researchs." (PMID 37205191, 2023). "Interestingly, the current study showed that cancer stromal TGFBI expression was strongly correlated with the presence of LPS in cancer cells." (PMID 37511547, 2023). "Soluble factors such as heparanase stimulates VEGF-C expression in cancer, while TGFBI induces activation of FAK signaling pathway in lymphatic endothelial cells (LECs), and increased expression of CCL21 on the surface of LECs to induce the dissociation of VE-cadherin junctions between LECs." (PMID 36906534, 2023). "Overexpression of miR-766-3p inhibits cancer growth by targeting TGFBI." (PMID 37205191, 2023). "The LPS-positive group showed significantly greater cancer stromal TGFBI expression (p < 0.0001), more HER2-negative cases (p = 0.012), greater PD-L1 expression (p = 0.0029), increased wnt3a signaling (p = 0.0028) and lower E-cadherin expression (p = 0.0055) (EMT marker) than the LPS-positive group." (PMID 37511547, 2023). "In summary, our study identifies an epigenetic mechanism by which the main eBL risk factors (EBV infection and AFB1 exposure) bring about the silencing of a cancer-related gene (TGFBI) and provides insight into molecular events potentially contributing to eBL development." (PMID 35267594, 2022). "The cancer-suppressive impact of miR-766-3p overexpression was attenuated by overexpressing TGFBI." (PMID 35083181, 2022). "Many reports have substantiated that TGFBI exerts a key role in cancer progression." (PMID 35083181, 2022). "However, we focused on the detection of the periostin POSTN and transforming growth factor beta-induced protein TGFBI proteins, which, in cancer cells, are regulated by the stem cell transcription factor Snail (SNAI1)." (PMID 33806753, 2021). "Besides, we analyze the correlation between TGFBI expression with various immune cell infiltration in different types of human cancers." (PMID 34671645, 2021). "Analysis revealed that aberrant TGFBI protein expression was detected in 20 cancer types." (PMID 34671645, 2021). "We also explored the associations of TGFBI expression with TMB and MSI in various types of cancer." (PMID 34671645, 2021). "Our results indicated that TGFBI is an oncogenic ECM formation protein that may serve as a valuable therapeutic target for new anti-cancer treatment strategies." (PMID 34671645, 2021). "They identified three proteins from these macrophage secretomes that could stimulate cancer cell migration, one of which was TGFBI." (PMID 34561272, 2021).
cancer (continued). "Here, for the first time, we conducted a pan-cancer analysis of TGFBI mRNA and protein expression and prognoses across various cancer types using several public databases such as, Gene Expression Omnibus (GEO), The Cancer Genome Atlas (TCGA), Oncomine, and Human Protein Atlas (HPA) databases." (PMID 34671645, 2021). "In CRC-LM samples, TGFBI could be detected frequently also in cancer cells (pan-cytokeratin-positive), although its expression remained predominant in stromal cells (vimentin-positive)." (PMID 33408771, 2021). "TGFBI might influence tumorigenesis in these cancer types by participating in the process of genetic alterations." (PMID 34671645, 2021). "Future studies should determine how more potent anti-TGFBI antibodies can be generated, and how TGFBI targeting could be combined with other therapies that affect cancer cell proliferation, metabolism or immunity." (PMID 33408771, 2021). "Previous work has shown that TGFBI is expressed by stromal fibroblasts and cancer cells." (PMID 32312959, 2020). "The role of TGFBI in cancer is still controversial and seems to be context‐dependent." (PMID 33080107, 2020). "Moreover, we found that not only the mRNA expression but also the CNV level of TGFBI ranked as the first highest of all types of cancer cell lines." (PMID 32406866, 2020). "These included many cancer-associated genes such as AKT2, HRAS, TGFBI and UBE2C." (PMID 32437477, 2020). "The expressions of TGFBI were different in these types of cancers." (PMID 32406866, 2020). "Furthermore, three DEGs (FCER1A, EDNRB, and TGFBI) in the model of relapse showed prognostic significance for predicting the survival of patients with cancer through Cox proportional hazards regression model-based survival analysis." (PMID 33138797, 2020). "Numerous cells, e.g., fibroblasts, corneal epithelial cells, smooth muscle cells and various cancer cells were demonstrated to induce TGFBI expression after transforming growth factor-β treatment, but also by interleukin-1, retinoic acid and tumor necrosis factor-α." (PMID 31514337, 2019). "Most of the TGFBI was localized in the cytoplasm in cancer tissues." (PMID 28229027, 2017). "Depending on the tissue, TGFBI functions as a promoter or suppressor of cancer growth." (PMID 20509890, 2010). "However, TGFBI is a trouble maker to push cancer far away from primary location." (PMID 36906534, 2023). "Similarly, the present study found that the presence of LPS was significantly correlated with cancer stromal TGFBI expression, which may have contributed to therapeutic resistance in patients with GC using nivolumab." (PMID 37511547, 2023). "First, although the study involved a bioinformatic analysis of TGFBI, including its expression, prognostic value, associations with immune cell infiltration, and mutation status in various human cancer types, there were no in vivo or in vitro experiments to validate the results." (PMID 34671645, 2021). "Similarly, TGFBI promotes proliferation and migration of cancer cells." (PMID 34884982, 2021). "Therefore, future studies should focus on the mechanisms of TGFBI in various human cancer types." (PMID 34671645, 2021). "Moreover, recombinant TGFBI induced apoptosis in cancer cells via integrin activation." (PMID 28106769, 2017). "Therefore, depending on the tissue, TGFBI functions as a promoter or suppressor of cancer growth." (PMID 25369402, 2014). "TGFBI may induce dissociation of VE-cadherin junctions, and eventual breakdown of the endothelial barrier via the integrin alpha-v beta-5 and the Src signal pathway, leading to increased cancer cell extravasation." (PMID 24708694, 2014). "Annexin A1 and TGFBI could be important therapy targets to manipulate to improve the efficacy of radio-and chemo-therapies for cancer patients, to reduce resistance to treatments and decrease recurrence of cancer." (PMID 23077482, 2012).
cancer (continued). "DEG analysis revealed higher expression levels of CRC markers such as CEACAM6, SPINK1, TGFBI and RSPO3 in the cancer cell group." (PMID 40355592, 2025). "We varied Cat D expression in various murine cancer cell lines, and an inverse correlation was observed between Cat D and TGFBI expression in B16F10, 4T1, E0771, and CT26 cancer cells." (PMID 38297161, 2024). "To evaluate the effect of TGFBI in Cat D KO cancer cells, we generated Cat D KO (CKO), TGFBI KO (TKO), and double KO of these genes (DKO) in E0771 and MDA-MB-231 cancer cells and confirmed the protein and mRNA expression of these proteins." (PMID 38297161, 2024). "Accordingly, Cat D knockdown also induced the upregulation of protein and mRNA expression and the secretion of TGFBI in both Caki and MBA-MB-231 cancer cells." (PMID 38297161, 2024). "Concerning CAV1, EFEMP1, FBLN2, TGFBI, or VDAC1, their actions are highly context-dependent and can vary across different cancer types and stages." (PMID 39201614, 2024). "TGFBI, on the other hand, is an extracellular matrix protein induced by TGF-β, playing a crucial role in cancer progression, including cell proliferation, angiogenesis, and apoptosis." (PMID 39192987, 2024). "Elevated TGFBI expression following Cat D deletion was confirmed in both Caki and MDA-MB-231 cancer cells." (PMID 38297161, 2024). "As for TGFBI, CFD, and MGP, MM patients displayed the highest median plasma concentration in comparison to the other cancer patients." (PMID 37835457, 2023). "TGFB2 was included in a four gene signature (FN1, TGFB2, TGFBR2, and TGFBI), as an indicator of CAF abundance, which predicted survival in TCGA pan-cancer cohort comprising 9356 patients from 32 cancer subtypes." (PMID 37296997, 2023). "Over-expression of TGFBI was markedly significantly to poor prognosis in KIRC in our study, which can stimulate the angiogenesis, metastasis, differentiation and invasion in cancer." (PMID 36035369, 2022). "Because TGFBI, an extracellular matrix (ECM) protein involved in cancer metastasis, is a well-known downstream target of the TGF-β pathway, we then studied the effect of LIN28B on other components of the TGF-β signalling pathway." (PMID 34548635, 2022). "The expression of TNFAIP3 was higher in immune cells, especially in epithelial carcinoma, macrophages, and CD8+ T‐cells (left), while TGFBI, IFI30, SPP1, and EREG were expressed more highly in macrophages than other cells." (PMID 35634956, 2022). "In this study, we presented evidence regarding the correlations between TGFBI expression and MSI and TMB across the TCGA pan-cancer." (PMID 34671645, 2021). "Immunohistochemical staining was performed for AXIN2, MYBL2, TGFBI, and SLC35D3, which represented that the part of cancer was deeper than that of normal." (PMID 35174154, 2021). "Additionally, we assessed the correlations between TGFBI expression and drug response in various human cancer cell lines from CellMiner database, which facilitates the integration and study of molecular and pharmacological data on the 60 different human cancer cell lines." (PMID 34671645, 2021). "Our results suggest that the relationships of TGFBI expression with TMB and MSI are diverse in those types of cancer." (PMID 34671645, 2021). "We assessed the correlation between the expression of TGFBI and OS, DSS, PFI, and DFI in different types of cancer using a single-variate Cox regression analysis based on TCGA database." (PMID 34671645, 2021). "As the nomenclature implies, TGFBI was first identified as a TGF-β-inducible gene, which has since been reported to regulate the premetastatic activity of TGF-β in some cancers." (PMID 33614494, 2020). "The binding of HA-MITF was nevertheless enhanced in 4C-HA-MITF cells, with multiple MITFBSs in proximity of several of these cancer-relevant genes (e.g., AXL, IL6, TGFBI, and EGFR,) compared to HA-MITF binding in 3C-HA-MITF." (PMID 32605315, 2020).
cancer (continued). "Among these target genes, KLK9, WNT3A, FGF18, FIBP, SOX12, TGFBI, and NEDD9 have been reported to participate in the development of human cancers." (PMID 33344223, 2020). "The epigenetic loss of DKK3 expression activates TGF-β signaling, leading to increased expression of pro-invasive factors, such as TGFBI and MMP2, which have the potential to promote progression to cancer." (PMID 29858602, 2018). "Particularly, transforming growth factor-beta-induced protein ig-h3 (Beta ig-h3) and peroxiredoxin-2 (PRDX2) overexpression in the secretome of cancer cell lines was detected and confirmed by Western blot." (PMID 28261610, 2017). "IPA also identified potential upstream regulators, which play a key role in cancer invasiveness: interleukin-6 (IL-6), IL1B and transforming growth factor, beta-induced (TGFBI) were the top three upstream activated regulators (P< .05)." (PMID 28632775, 2017). "In this study, several of the differentially expressed molecules identified, including TGFBI, NES, SNCA, and HSPA12A, have demonstrated roles in GBM and other cancers." (PMID 29228611, 2017). "In accordance with our recent study, DIO1 expression resulted also in suppression of TGFBI, and several other proteins (e.g. PODXL, CD74) that promote RCC progression or act as oncogenic proteins in other cancers (e.g. FMNL2, APBB1IP, ASAP1, and LRRFIP1)." (PMID 29272308, 2017). "In addition, it has been suggested that SPARC secreted by macrophages increases cancer cell migration and metastasis in an integrin-dependent manner, consistent with our own results, thus SPARC may also influence cancer dissemination in a TGFBI-dependent manner." (PMID 27622658, 2016). "Thus, silencing of the TGFBI promoter by hypermethylation would result in a deficiency of the gene product, which in turn may lead to the disruption of cell-ECM interaction and contribute to invasion and metastasis of cancer cells." (PMID 18834524, 2008). "Together, these findings demonstrate the pivotal role of TGFBI in BLCA's stemness maintenance and BLCA progression, highlighting that the inhibition of the TGFBI/GDF15 axis is a potential therapeutic strategy for the amelioration of cancer chemotherapy." (PMID 41684953, 2026). "For neuroinvasion—a hallmark of PDAC—scRNA-seq combined with spatial transcriptomics mapping identified two highly invasive cancer cell subpopulations: D09_Ductal-CEACAM6 (basal-like) and D04_Ductal-GABRP (neurotransmitter-responsive), along with TGFBI+ Schwann cell subpopulations induced by TGFβ1." (PMID 41463034, 2025). "In fact, even though Cat D KO cancer cells resulted in a reduction in metastatic potential in NOD-SCID mice, an immunodeficient mouse strain, TGFBI blockade failed to or marginally recovered the reduced metastatic potential of the Cat D KO cancer cells." (PMID 38297161, 2024). "Additionally, the addition of Cat D restored the protein, mRNA, and secretory levels of TGFBI in both Caki and MDA-MB-231 Cat D KO cancer cells." (PMID 38297161, 2024). "We examined whether the gain-of-function of Cat D could regulate the expression of TGFBI and EMT markers in cancer cells." (PMID 38297161, 2024). "The lack of an effect of TGFBI treatment on TAM polarization under culture conditions without CM further highlighted the biological necessity of TGFBI-mediated CCL20 in CM from Cat D KO cancer cells." (PMID 38297161, 2024). "Additionally, transforming growth factor beta-induced protein (TGFBI, or βig-H3) is a matrix protein determined by TGFβ1 and secreted into ECM by various cancers." (PMID 36906534, 2023). "In melanoma, TGFBI hinders cell adhesion to fibronectin, collagen-I, and laminin whereas co-localized with fibrillar fibronectin/TNC/periostin structures which favors invasive state of cancer." (PMID 36906534, 2023). "Next, same approach was used to evaluate TGFBI and HYALI in the other 32 TCGA cancer types." (PMID 34869001, 2021).